JUN-DT (JUN divergent transcript)
Synonyms: LOC101926907; formerly LINC01135; LINC01358
Gene: Long non-coding RNA gene on chromosome 1 (58,784,166 to 59,240,555, forward strand). Ensembl gene ENSG00000234807.
Diseases named in the same sentence as JUN-DT in open-access papers:
JUN-DT is named in the same sentence as 2 diseases in open-access papers, as found by Europe PMC text mining. Sharing a sentence is not in itself a finding about the gene and the disease.
JUN-DT shares sentences with these, for which no sentence is quoted: cancer (1 paper); prostatic cancer (1).